MTMR11 (myotubularin related protein 11)
Synonyms: CRA
Tractability: No criterion of Open Targets' tractability assessment is met for any kind of drug.
Gene: Protein-coding gene on chromosome 1 (149,928,651 to 149,937,523, reverse strand). Ensembl gene ENSG00000014914.
Subcellular location (Human Protein Atlas): Centrosome
Gene Ontology:
Cellular component: cytoplasm; extracellular exosome; membrane
Genetic constraint (gnomAD): Loss-of-function variants: 84 observed, 100.85 expected, observed/expected ratio (o/e) 0.83, 90% interval 0.7 to 1. The upper end of that interval is the gene's LOEUF score, 1, which puts it in group 4 of 6, group 1 being the genes least tolerant of losing a copy. Missense variants: 786 observed, 889.73 expected, observed/expected ratio (o/e) 0.88, 90% interval 0.83 to 0.94. Synonymous variants: 326 observed, 336.58 expected, observed/expected ratio (o/e) 0.97, 90% interval 0.88 to 1.06.
Homologues: Orthologues: chimpanzee MTMR11 (99% identical), macaque MTMR11 (97% identical), pig MTMR11 (89% identical), dog MTMR11 (88% identical), rat Mtmr11 (86% identical), guinea pig MTMR11 (86% identical), mouse Mtmr11 (85% identical), rabbit MTMR11 (84% identical), zebrafish mtmr11 (40% identical), tropical clawed frog mtmr11 (38% identical), Drosophila melanogaster CG14411 (27% identical), Caenorhabditis elegans mtm-10 (19% identical), and 10 more. Paralogues in human: MTMR10 (31% identical), MTMR12 (27% identical), SBF1 (21% identical), SBF2 (20% identical), MTMR2 (20% identical), MTMR9 (20% identical), MTMR4 (19% identical), MTMR1 (19% identical), MTMR3 (18% identical), MTM1 (18% identical), MTMR7 (16% identical), MTMR6 (16% identical), and 1 more.
Diseases named in the same sentence as MTMR11 in open-access papers:
MTMR11 is named in the same sentence as 10 diseases in open-access papers, as found by Europe PMC text mining. Sharing a sentence is not in itself a finding about the gene and the disease. The quoted sentences say what the papers report.
breast carcinoma (3 papers, 2015 to 2024). "One study has also reported altered expression levels of MTMR11 in breast cancer cells." (PMID 35884425, 2022). "We found nominal evidence of association with breast cancer overall for LoF variants in three genes (ZFAND1, TMEM206/PACC1, and TYRO3), with ER-negative breast cancer in two genes, DNAH11 and PARP2, and with ER-positive disease in four genes LAMC3, MTMR11, EPN3, and SLC22A10." (PMID 35884425, 2022). "Of these twenty, three showed evidence of association with LoF variants for overall breast cancer (ZFAND1, TYRO3, TMEM206/PACC1), and a further six with breast cancer subtypes (DNAH11, PARP2, LAMC3, MTMR11, EPN3, SLC22A10)." (PMID 35884425, 2022). "One of the genes, MTMR11 (Entrez gene ID: 10903), is a member of the protein tyrosine phosphatase family, and has been shown to be downregulated in some HER2 breast cancers." (PMID 25779658, 2015). "Among those genes, most were described in the functional analyses of previously published MD GWAS32,47,48, such as MKL1/MRTFA (rs73169097 – negative ‘null’ cluster SNP) and MTMR11 (rs11205303), both of which have dense phenotype-increasing effect but are protective against breast cancer." (PMID 38740751, 2024).
glioma (1 paper, 2024). A benign or malignant brain and spinal cord tumor that arises from glial cells (astrocytes, oligodendrocytes, ependymal cells). "Moreover, DUSP11, LPIN3, MTMR11, HDDC2, and PLPPR3 have not been queried for glioma-related studies." (PMID 39830513, 2024).
cancer (1 paper, 2018). A tumor composed of atypical neoplastic, often pleomorphic cells that invade other tissues. "Myotubularin related protein 11 (MTMR11) was rarely reported in cancer." (PMID 30662454, 2018).
tumor (1 paper, 2019). "Several genes splicing events, including KIAA1715/56096/AP, ZNF567/49415/AP, NTMT1/87861/AP, ANAPC15/17570/AD, SRPK2/81284/ES, MTMR11/7413/AP, FNIP2/70999/AP, and TNC/87336/ES, differed significantly between tumor and normal samples." (PMID 31552163, 2019).
MTMR11 also shares sentences with these, for which no sentence is quoted: atherosclerosis (1 paper); colonic carcinoma (1); dwarfism (1); Myotubular myopathy (1); osteoarthritis (1); type 2 diabetes (1).